NBL1 (NBL1, DAN family BMP antagonist)
Description:
Possible candidate as a tumor suppressor gene of neuroblastoma. May play an important role in preventing cells from entering the final stage (G1/S) of the transformation process.
Synonyms: DAN; DAND1; D1S1733E; NB; NO3; C1orf151-NBL1; MINOS1-NBL1; MICOS10-NBL1
Tractability: Antibody: UniProt places it where antibodies can reach, with medium confidence; UniProt predicts a signal peptide or a membrane-spanning region; its Gene Ontology location is reachable by antibodies, with medium confidence.
Gene: Protein-coding gene on chromosome 1 (19,596,979 to 19,658,456, forward strand). Ensembl gene ENSG00000158747.
Subcellular location: Secreted
Gene Ontology:
Molecular function: identical protein binding; protein binding; BMP binding; morphogen activity; receptor ligand activity; protein sequestering activity; receptor ligand inhibitor activity
Biological process: negative regulation of BMP signaling pathway; determination of dorsal identity; negative regulation of monocyte chemotaxis; nervous system development; neuron projection morphogenesis; positive regulation of neuron differentiation; signal transduction
Cellular component: extracellular region
Genetic constraint (gnomAD): Loss-of-function variants: 9 observed, 16.04 expected, observed/expected ratio (o/e) 0.56, 90% interval 0.34 to 0.98. The upper end of that interval is the gene's LOEUF score, 0.98, which puts it in group 4 of 6, group 1 being the genes least tolerant of losing a copy. Missense variants: 186 observed, 227.23 expected, observed/expected ratio (o/e) 0.82, 90% interval 0.73 to 0.92. Synonymous variants: 84 observed, 93.12 expected, observed/expected ratio (o/e) 0.9, 90% interval 0.75 to 1.08.
Homologues: Orthologues: chimpanzee NBL1 (100% identical), macaque NBL1 (99% identical), dog NBL1 (94% identical), pig NBL1 (93% identical), mouse Nbl1 (93% identical), guinea pig NBL1 (92% identical), rat Nbl1 (92% identical), rabbit NBL1 (91% identical), tropical clawed frog nbl1 (66% identical), Caenorhabditis elegans F35B12.10 (17% identical). Paralogues in human: GREM1 (21% identical), GREM2 (21% identical).
Diseases named in the same sentence as NBL1 in open-access papers:
NBL1 is named in the same sentence as 34 diseases in open-access papers, as found by Europe PMC text mining. Sharing a sentence is not in itself a finding about the gene and the disease. The quoted sentences say what the papers report.
neuroblastoma (12 papers, 2008 to 2025). Neuroblastoma (NB) is the most common solid, extracranial childhood tumor. "The bone morphogenetic protein antagonist Nbl1 plays a role in the development of multiple tissues including the forebrain and has been associated with neuroblastoma formation." (PMID 38039370, 2023). "NBL1, a member of the family of differential screening-selected gene aberrative in neuroblastoma (DAN), is associated with not only neuroblastoma but also with remodelling of vessels by inhibiting pulmonary arterial smooth muscle cell proliferation." (PMID 29596467, 2018). "NBL1 is a secreted protein with roles in cell proliferation and differentiation, frequently researched in neuroblastoma and tumor biology." (PMID 40624693, 2025). "NBL1 was initially identified as a tumor suppressor in a neuroblastoma cell line and was later found important for nervous system and bone development." (PMID 32984236, 2020). "Neuroblastoma suppressor of tumorigenicity 1 (NBL1) is a secreted protein which belongs the differential screening-selected gene aberrative in neuroblastoma (DAN) subfamily." (PMID 27474499, 2016). "Common genes include Jagged 1 (Jag1), Tetraspanin 2 (Tspan2), neuroblastoma, suppression of tumourigenicity 1 (Nbl1) and N-myc downstream regulated gene 2 (Ndrg2)." (PMID 25545425, 2015). "Neuroblastoma, suppression of tumorigenecity, (Nbl1, also named Dan or NO3) is a member of a class of secreted glycoproteins which act as inhibitors of the transforming growth factor beta and bone morphogenic protein pathway." (PMID 22384097, 2012). "NBL1 is an antagonist of BMP2, also known as neuroblastoma (DAN), a tumor suppressor that plays essential roles in numerous biological functions." (PMID 35487890, 2022).
pancreatic carcinoma (2 papers, 2012 to 2026). "Therapeutically, NBL1's dual role (BMP antagonist in pancreatic cancer versus Stat3 activator in OC) highlights the need for tissue-specific strategies." (PMID 41158754, 2026). "In line with this, Nbl1 is found to be overexpressed in pancreatic carcinoma." (PMID 22384097, 2012).
prostate carcinoma (2 papers, 2008 to 2024). A carcinoma that arises from epithelial cells of the prostate gland. "In another study, researchers constructed a miRNA-mRNA regulatory network containing miR-106b-5p to identify genes such as TMEM100, FRMD6, NBL1, and STARD4 for the diagnosis and prognosis of prostate cancer patients." (PMID 38818039, 2024).
Trichinella spiralis infection (2 papers, 2017 to 2022). "NBL1 is a newborn larva stage-specific serine protease and C-terminal part of NBL1 (NBL1-C) can be useful for the early diagnosis of trichinellosis in pigs, invasion of host cells and protective immune responses during Trichinella infection." (PMID 28620363, 2017). "The Ts-NBL1 protein is considered to be a potential key “parakine” involved in the early invasion of the muscle fiber and its transformation into a feeder cell during Trichinella spiralis infection." (PMID 35320836, 2022).
atherosclerosis (1 paper, 2018). A disease characterized by the build-up of fatty material and calcium deposition in the arterial wall resulting in partial or complete occlusion of the arterial lumen. "Serum NBL1-Ab level was measured by amplified luminescence proximity homogeneous assay and its association with clinical variables related to atherosclerosis was evaluated." (PMID 29596467, 2018). "Other studies suggest that BMP2 and BMP4 are linked to the development of atherosclerosis, and BMP antagonist neuroblastoma suppressor of tumorigenicity 1 (NBL1, accession number X66872.1) specifically antagonizes BMP2, BMP4 and BMP14." (PMID 29596467, 2018). "Thus, it is conceivable that there exists a functional relationship between NBL1 and atherosclerosis." (PMID 29596467, 2018). "Therefore, NBL1-Ab may have the potential to be an optional marker of atherosclerosis in addition to other conventional investigations." (PMID 29596467, 2018). "As NBL1 is a specific antagonist of BMP2 and BMP4, both of which promote atherosclerosis, NBL1 is capable to inhibit atherosclerosis." (PMID 29596467, 2018). "Therefore, monitoring circulating NBL1-Ab levels might be useful for evaluating the risk of lethal events in patients with OSA; however, prospective cohort studies are needed to confirm its effectiveness as a marker for atherosclerosis risk." (PMID 29596467, 2018).
end-stage renal disease (1 paper, 2024). "This is further corroborated by the fact that increased levels of two of these proteins were previously found to increase risk of CKD or end-stage renal disease (ESRD) in prospective studies in persons with diabetes (TNF sR-I (TNFRSF1A), NBL1 (DAN)." (PMID 38801599, 2024).
epilepsy (1 paper, 2025). A brain disorder characterized by episodes of abnormally increased neuronal discharge resulting in transient episodes of sensory or motor neurological dysfunction, or psychic dysfunction. "MR analysis identified causal relationships, such as NBL1 in epilepsy, TPGS2 in ischemic stroke, and SERINC2 in VaD." (PMID 40624693, 2025). "The IVW model indicated a significant causal relationship between NBL1 and the epilepsy outcome (OR = 0.722, 95% CI = 0.582–0.897, p = 0.003), suggesting that an increase in the exposure factor is causally linked to a decrease in the outcome measure." (PMID 40624693, 2025). "In epilepsy, mapping our m6A-associated genes (e.g., PARP1, NBL1, RPL14) to their proteomic counterparts identified causal links to proteins such as ST6GALNAC5, CTNNA2, and TOM1L1, highlighting specific m6A-driven regulatory cascades at the protein level." (PMID 40624693, 2025). "Among all exposure genes, RP11-267M23.4, ENTPD3-AS, ZNF619, and RPL14 were demonstrated as risk factor to epilepsy, while NBL1, RNF157, and PARP1 were protective factors to epilepsy." (PMID 40624693, 2025). "We found that RP11-267M23.4, NBL1, ENTPD3-AS, RNF157, ZNF619, RPL14, and PARP1 showed causal relationship to epilepsy." (PMID 40624693, 2025). "Additionally, our MR analysis identified causal relationships between specific genes and disease outcomes, such as NBL1 in epilepsy, TPGS2 in ischemic stroke, and SERINC2 in VaD." (PMID 40624693, 2025). "In the MR analysis with epilepsy as the outcome, we identified seven positive results: RP11-267M23.4, NBL1, ENTPD3-AS1, RNF157, ZNF619, RPL14, and PARP1." (PMID 40624693, 2025).
lung adenocarcinoma (1 paper, 2026). A carcinoma that arises from the lung and is characterized by the presence of malignant glandular epithelial cells. "In pancreatic ductal adenocarcinoma, NBL1 inhibits tumor growth by antagonizing bone morphogenetic protein 2/4 (BMP2/4) signaling and suppressing EMT, whereas in lung adenocarcinoma, NBL1 acts as a transcriptional target of miR-1301-3p to suppress metastasis." (PMID 41158754, 2026). "Neuroblastoma suppressor of tumorigenicity 1 (NBL1), also known as DAN, has been widely reported as a tumor suppressor in multiple cancers, including pancreatic cancer and lung adenocarcinoma." (PMID 41158754, 2026).
lung carcinoma (1 paper, 2026). "Contrary to its well-documented tumor-suppressive roles in pancreatic and lung cancers, our study reveals a paradoxical oncogenic function of NBL1 in OC." (PMID 41158754, 2026).
metastatic tumors (1 paper, 2026). "Notably, NBL1 expression level was significantly higher in metastatic tumors than in primary tumors." (PMID 41158754, 2026).
oligoarticular JIA (1 paper, 2022). "S100A4, TIMP3, and NBL1 are overexpressed in pre-extension oligoarticular JIA FLS compared to polyarticular JIA FLS." (PMID 36167601, 2022).
tumor (15 papers, 2012 to 2026). "We observed statistically significant associations for HIV total DNA and two tumor suppressor genes, NBL1 and P3H3, using a stringent false discovery rate q<0.05." (PMID 38019897, 2023). "Consistently, in vivo experiments showed that OE NBL1 mice had higher tumor burden, suggesting that NBL1-mediated apoptosis inhibition contributes to aggressive metastasis." (PMID 41158754, 2026). "The OE NBL1 group exhibited significantly increased primary tumor burden and extensive metastatic lesions." (PMID 41158754, 2026). "Another two tumor suppressor genes Btg1 and Nbl1 were also significantly upregulated following 4-OHA treatment." (PMID 37056757, 2023). "NSE overexpression enhanced tumor sphere-forming capacity, which was counteracted by NBL1 overexpression." (PMID 35487890, 2022). "Previous studies have showed that the expression of NBL1 was significantly reduced in a wide variety of transformed cells and human tumour specimens." (PMID 27474499, 2016). "Neuroblastoma suppressor of tumorigenicity 1 (NBL1) has been previously shown to induce growth inhibition in tumour cells." (PMID 27474499, 2016). "Our data establish NBL1 as a critical driver of OC metastasis through dual mechanisms: i) direct activation of Jak/Stat3 signaling via physical interaction, and ii) suppression of anti-tumor immunity by limiting T cell infiltration." (PMID 41158754, 2026). "The analysis of NBL1 function by transfection of cultured cell revealed that NBL1 may suppress the transformed phenotype and delay entry into the S-phase in tumour cells, suggesting that NBL1 has a tumour-suppressive activity." (PMID 27474499, 2016). "Additionally, nbl1 was proposed to be a candidate tumor marker for prostate cancer." (PMID 32251302, 2020). "Furthermore, elevated NBL1 counteracted the promotion of NSE overexpression on SCLC cell proliferation in vitro and tumor growth in vivo." (PMID 35487890, 2022). "In addition, immunohistochemical analysis of the expression levels of NSE, NBL1, and ALDH1A1 in the tumor tissues of patients with SCLC showed that the expression level of NSE was positively correlated with that of ALDH1A1 and negatively correlated with that of NBL1." (PMID 35487890, 2022).
cancer (5 papers, 2019 to 2026). A tumor composed of atypical neoplastic, often pleomorphic cells that invade other tissues. "The pan-cancer analysis revealed significant variations in NBL1 expression linked to immune cell infiltration and gene mutation." (PMID 41158754, 2026). "Given the strong correlation between NBL1 and cancer-associated fibroblast infiltration, future work should dissect how NBL1 modulates stromal interactions to foster metastatic niches." (PMID 41158754, 2026). "Additionally, NBL1 showed a positive correlation with cancer-associated fibroblasts across various cancers, including OC." (PMID 41158754, 2026). "The expression of NBL1 revealed a significant increase in the transcoelomic spread cancer samples compared with those from the primary sites." (PMID 41158754, 2026). "To investigate the biological role of NBL1 in various cancers, we analyzed its expression profiles using the TIMER2.0 online database, finding high expression in 5 cancer types and low in 11 compared with normal tissues." (PMID 41158754, 2026). "Four of these (Sp1, NBL1, MINOS1-NBL1, and MAPK1) were predicted to be target genes of miR-2110; hence, we selected miR-2110 according to its probable cancer-related downstream pathway." (PMID 34145213, 2021). "First, while we identified NBL1's negative correlation with T cell infiltration via TIMER2.0 and flow cytometry, the direct impact of NBL1 on cancer-associated fibroblasts or myeloid-derived suppressor cells remains unexplored." (PMID 41158754, 2026). "Indeed, except for that PTCH1, KLK10, TBRG1, NBL1 and EXT1 did not act on gene expression in stage-2 cancer, the other 21 TS gene had larger positive network effects on gene expression than negative network effects in cancer." (PMID 33580150, 2021). "First, TBRG1, PICH1, NBL1, TRIM13 and APC did not impact gene up-expression in cancer." (PMID 33580150, 2021).
infection (2 papers, 2020 to 2021). The state of being infected such as from the introduction of a foreign agent such as serum, vaccine, antigenic substance or organism. "DAB staining indicated that pathogen-induced ROS generation was blocked in nbl1, and investigation of the infection process displayed that M. oryzae strain 14–856-2 invaded and expanded rapidly on nbl1 leaves." (PMID 33423130, 2021).
neurodegenerative disease (1 paper, 2020). A disorder of the central nervous system characterized by gradual and progressive loss of neural tissue and neurologic function. "There is hitherto no relation described with NBL1 and neurodegenerative diseases or with manganese or iron." (PMID 32984236, 2020).
NBL1 also shares sentences with these, for which no sentence is quoted: Hypertension (2 papers); autism (1); colorectal cancer (1); coronary artery disease (1); diabetes (1); endometriosis (1); fibrosis (1); hyperlipidemia (1); ischemic stroke (1); mammary carcinoma (1); obstructive sleep apnea (1); ovarian carcinoma (1); pancreatic ductal adenocarcinoma (1); periodontitis (1); psychiatric disorder (1); schizophrenia (1); small cell lung carcinoma (1); Stroke (1); uveal melanoma (1).